RET (ret proto-oncogene)
Diseases named in the same sentence as RET in open-access papers (continued):
Sharing a sentence is not in itself a finding about the gene and the disease.
medullary thyroid carcinoma (continued). "In this cohort study of 506 544 unrelated individuals, incidentally identified moderate-risk RET variants were associated with substantially lower medullary thyroid cancer risk compared with clinically ascertained cases with suspected multiple endocrine neoplasia type 2 (2.8%-19.0% vs 98.2%)." (PMID 40577012, 2025). "Notably, given the high incidence of RET rearrangement mutations in medullary thyroid cancer (MTC), existing research has focused primarily on this specific subtype." (PMID 41278287, 2025). "Among 77 RET pathogenic variant carriers (52 [67.5%] of whom underwent Sanger sequencing as part of the MyCode Genome Screening and Counseling Program to confirm the variant), 10 were found to have medullary thyroid cancer." (PMID 40577012, 2025). "Consequently, the underlying causes of wild-type RET overexpression in medullary thyroid cancer samples, such as aberrations in RET regulatory factors, necessitate further investigation." (PMID 41373459, 2025). "This case report describes a 13-year-old girl with familial medullary thyroid cancer linked to germline rearranged during transfection (RET) proto-oncogene mutation, with a high risk of early onset and aggressive disease, who underwent total thyroidectomy with prophylactic neck dissection." (PMID 40677447, 2025). "Selpercatinib may represent an effective therapeutic option for patients with medullary thyroid carcinoma driven by uncommon RET mutations, including mutations in the transmembrane domain." (PMID 40638225, 2025). "Mutation at RET gene codons 918 and 634 is strongly correlated with medullary thyroid cancer." (PMID 39235852, 2024). "The earliest diagnosis of medullary thyroid carcinoma and lichen amyloidosis was reported in 2002 in an asymptomatic 5-year-old child coming from a family with multiple endocrine neoplasia type 2 that harbored RET-Cys634Trp (TGC->TGG) pathogenic variant." (PMID 39585007, 2024). "Medullary Thyroid Carcinomas evaluated for RET splice site variants." (PMID 38566816, 2024). "Therefore, the gene panel testing of mediastinal lymph node metastasis with a major proportion of medullary carcinoma components was performed to determine the RET gene somatic mutations." (PMID 38647958, 2024). "The REarranged during Transfection (RET) oncogene was first discovered in 1980 and subsequently identified as a pivotal cancerogenic determinant for papillary and medullary thyroid carcinomas and other malignancies, paving the way for new diagnostic and therapeutic strategies." (PMID 39211557, 2024). "In medullary thyroid cancer, RET and RAS driver mutations are mutually exclusive, and a similar relationship may exist in Eμ-Ret B-ALL." (PMID 38519798, 2024). "Multiple Endocrine Neoplasia type 2B (MEN2B) is an autosomal dominant cancer syndrome caused by a mutation in rearranged during transfection (RET) proto-oncogene and includes medullary thyroid carcinoma, pheochromocytoma, gastrointestinal neuromas, and mucosal ganglioneuromas." (PMID 38562350, 2024). "The majority (60%) of medullary thyroid cancers (MTCs) are driven by mutations in the rearranged during transfection (RET) proto-oncogene, leading to inappropriate activation of growth factor signalling pathways such as the mitogen-activated protein kinase (MAPK) pathway." (PMID 38804700, 2024). "Non-medullary thyroid carcinomas evaluated for RET splice site variants." (PMID 38566816, 2024). "Pathological data associated with RET splice site variant positive medullary thyroid carcinomas." (PMID 38566816, 2024). "Additionally, the RET gene heterozygous change (c.2410G > A), (p.Val804Met) stands as the most prevalent pathogenic variant associated with medullary thyroid carcinoma." (PMID 38802890, 2024). "Consequently, larotrectinib and entrectinib have been granted tumor-agnostic FDA approvals and selpercatinib and pralsetinib are approved for both NSCLC and papillary or medullary thyroid cancers with RET fusions or mutations, respectively." (PMID 37168365, 2023).
medullary thyroid carcinoma (continued). "Three patients with RET mutation underwent prophylactic total thyroidectomy with the histological diagnosis of medullary thyroid cancer (all three patients were 6 years old or less); the preoperative calcitonin levels were respectively 3.4 pg/ml, 7 pg/ml and 2.2 pg/ml (mean 4.2 pg/ml)." (PMID 36936146, 2023). "Similarly, the three patients who underwent prophylactic total thyroidectomy for activating RET gene mutation had a definitive histological diagnosis of medullary carcinoma." (PMID 36936146, 2023). "RET fusions are observed in about 1–2% of non-small cell lung cancers (NSCLCs) and 5–10% of papillary thyroid cancers (TCs), and RET mutations occur in approximately 70% of patients with medullary thyroid cancer (MTC)." (PMID 38201566, 2023). "Our work reports a much higher malignancy rate among indeterminate TIR 3B lesions than observed in the adult population and the three patients who underwent prophylactic total thyroidectomy for activating RET gene mutation had all a definitive histological diagnosis of medullary carcinoma." (PMID 36936146, 2023). "The strongest association has been defined with MEN2A, which is a rare autosomal dominant endocrine tumor syndrome, characterized by medullary thyroid carcinoma, pheochromocytoma and parathyroid tumors, caused by a heterozygous pathogenic mutation in the RET gene." (PMID 38137741, 2023). "Also, PCC is rarely the first clinical manifestation of MEN2 and, when this occurs, is most frequently associated with RET mutations in the codon 634, whose patients invariably have medullary thyroid carcinoma at the ages at which they were diagnosed with PCC." (PMID 36187102, 2022). "All patients with RET mutations had medullary thyroid cancer (MTC)." (PMID 35304457, 2022). "For example, RET mutation is frequently found in medullary carcinoma." (PMID 36544713, 2022). "In the case of medullary carcinoma, RET mutation is commonly identified, supporting a distinct clonal origin in the case of a coexisting papillary tumor, as different cellular types might be affected simultaneously." (PMID 36212468, 2022). "Drugs targeting medullary thyroid cancers and RET-mutated NSCLC with relevant clinical trial data." (PMID 36091144, 2022). "As regards RET-positive cancers, RET gatekeeper mutations at the V804 residue (V804L and V804M) primarily occur as germline mutations in sporadic medullary thyroid cancers and in about 2% of MEN2 where they act as primary driver mutations and cause intrinsic resistance to several MKIs." (PMID 33806299, 2021). "Furthermore, clinical activity has already been observed with selpercatinib in patients with medullary thyroid cancers harboring the RET V804M gatekeeper mutation." (PMID 33771190, 2021). "The aim of this study was to identify germline mutation of the RET (rearranged during transfection) gene in patients with medullary thyroid carcinoma (MTC) and their first-degree relatives to find presymptomatic carriers for possible prophylactic thyroidectomy." (PMID 34777782, 2021). "Moreover, point mutations in RET are responsible for multiple endocrine neoplasia types 2A and 2B, which can develop into medullary thyroid cancer and pheochromocytoma." (PMID 33150251, 2020). "In the phase I component of the LIBRETTO-001 trial investigating LOXO-292, an ATP-competitive highly selective small molecule RET inhibitor, LOXO-292 showed robust antitumor activity in patients with RET fusion-positive PTC and NSCLC, and RET mutation-positive medullary thyroid cancer." (PMID 32292131, 2020). "Activating mutations in RET lead to the cancer syndrome multiple endocrine neoplasia type 2, which is associated with the occurrence of multiple tumours, including the highly metastatic medullary thyroid carcinoma." (PMID 30333215, 2018). "Indeed, activating mutations of the RET gene are responsible for medullary thyroid carcinomas, and RET/PTC rearrangements are associated with some 5 to 25% of thyroid papillary carcinomas." (PMID 30186235, 2018).
medullary thyroid carcinoma (continued). "Sixty-five patients (60.2%) had a sporadic medullary thyroid carcinoma, 39 patients (36.1%) had MEN2a and 4 patients (3.7%) had MEN2b, from 3 patients the RET-mutation status was unknown." (PMID 28404916, 2017). "Somatic mutations in RET are also found in 30–50% of patients with medullary thyroid cancer." (PMID 29140271, 2017). "RET minor allele frequency polymorphisms in medullary thyroid carcinoma patients." (PMID 26829565, 2016). "Notably, 8 RET mutations occurred specifically at E768, R844, S904, R912 and M918 (data not shown), which corresponded to hereditary RET mutated sites in familiar medullary thyroid carcinoma and multiple endocrine neoplasia type 2B." (PMID 26078337, 2015). "This hypothesis is supported by parallel evidence observed in medullary thyroid carcinoma patients with activating RET mutations, in which over 50 unique mutations are described." (PMID 26253102, 2015). "In addition, RET mutations are present in the germline of nearly all patients with hereditary forms of medullary thyroid cancer (MTC) and approximately 50% of patients with sporadic MTC have somatic RET mutations that are associated with a worse outcome." (PMID 25881079, 2015). "In the specific cases of RET-associated pheochromocytoma, young relatives carriers of RET mutations may undergo prophylactic thyroidectomy to prevent the development of medullary thyroid carcinoma." (PMID 24899893, 2014). "Interestingly, vandetanib has been shown recently to be well-tolerated and highly active in children with locally advanced or metastatic medullary thyroid cancer in the context of a RET M918T mutation." (PMID 24811913, 2014). "In medullary thyroid carcinoma, RET oncogene mutation correlates with a worse outcome." (PMID 23883275, 2013). "In 1993 germline mutations of RET were discovered in hereditary medullary thyroid cancer." (PMID 23514096, 2013). "When serum calcitonin is negative a cytomorphologic analysis of fine needle aspiration and a determination of RET proto-oncogene mutations are two diagnostic tools which are available for detection and accurate management of patients in whom medullary thyroid carcinoma is expected." (PMID 17184544, 2006). "Furthermore, germline RET testing is recommended even in patients who appear to have sporadic medullary thyroid carcinoma, as occult germline mutations are found in 1–7% of such cases and may modify both patient management and familial screening." (PMID 41465145, 2025). "Importantly our data suggest that medullary thyroid cancer onset in moderate-risk RET variant carriers occurs predominantly in adulthood in genotype-first and even in phenotype-first approaches (with 100% and 84% developing medullary thyroid cancer after age 30 years, respectively)." (PMID 40577012, 2025). "The aim of the research was to characterize RET mutations in patients with medullary thyroid carcinoma (MTC) in Romania, considering their relevance for tyrosine kinase inhibitor therapy." (PMID 41514606, 2025). "Conversely, pathogenic variants in the RET gene are associated with MEN2A, MEN2B, familial medullary thyroid carcinoma (MTC), and Hirschsprung disease." (PMID 39512978, 2024). "Interestingly, one patient harboring RET-C634R pathogenic variant had, not only medullary thyroid carcinoma and pheochromocytoma, but also primary hyperparathyroidism, as seen in a single case according to our series (being the rarest component among the endocrine tumour tumor in the syndrome)." (PMID 39585007, 2024). "In patients at increased risk of medullary thyroid cancer or mutations in the RET proto-oncogene and MEN2, as well as with a family history of thyroid diseases, prolonged use of GLP-1RA could contribute to the formation of thyroid tumors, particularly those originating from thyroid C-cells." (PMID 39598383, 2024). "A patient with metastatic medullary thyroid carcinoma (MTC) harboring a RET activation loop D898_E901del mutation was treated with selpercatinib." (PMID 38438731, 2024).
medullary thyroid carcinoma (continued). "The RET proto-oncogene’s gain-of-function mutation is a major cause of medullary thyroid carcinoma (MTC), which is part of multiple endocrine neoplasia type 2 (MEN2) syndrome." (PMID 37046823, 2023). "In addition to clinical findings in medullary thyroid cancer evaluation, RET proto-oncogene mutation screening is highly recommended to determine genotype-phenotype risks and to distinguish between sporadic and familial cases in terms of maintenance of the disease." (PMID 33777662, 2021). "For example, medullary thyroid carcinoma (MTC) and multiple endocrine neoplasia (MEN2A, MEN2B) occur due to sporadic mutation or germline RET mutation." (PMID 33525725, 2021). "Hereditary medullary thyroid carcinoma (MTC) is mainly caused by germline mutations in the RET proto-oncogene, which accounts for 20–30% of all MTC according to foreign studies." (PMID 32408902, 2020). "Germline RET variants are responsible for approximately 25% of medullary thyroid carcinoma (MTC) cases." (PMID 33167350, 2020). "Moreover, XPO5 was overexpressed in medullary thyroid carcinomas harboring RET mutations." (PMID 31371628, 2019). "Interestingly, mutation G533C is located in the RET extracellular domain and consists in the replacement of a glycine amino acid with a cysteine as often observed in families with familial medullary thyroid carcinoma (FMTC) or Multiple Endocrine Neoplasia (MEN) 2A." (PMID 29665843, 2018). "We investigated a case of an aggressive, apparently sporadic medullary thyroid carcinoma (MTC) harboring a somatic RET p.Cys634Arg mutation (a known MTC driver)." (PMID 30321177, 2018). "Tenascin C, EGFR, E-cadherin, TTF-1-expression, and their correlations with RET mutation status were investigated in 30 patients with medullary thyroid carcinoma (MTC) (n = 26) or C-cell hyperplasia (n = 4)." (PMID 27409604, 2016). "Missense germline and somatic point mutations of RET are associated to familial (95%) and sporadic (50%) cases of medullary thyroid carcinoma (MTC), respectively." (PMID 26046350, 2015). "Interestingly, RET mutations have been found in both multiple endocrine neoplasia type 2, characterized by medullary thyroid carcinoma (MTC), and primary colorectal cancer, supporting its oncogenic function in thyroid carcinoma and tumor-suppressing function in colon cancer, respectively." (PMID 23109895, 2012). "Familial medullary thyroid carcinoma (MTC) frequently exhibits germline RET mutations, while the RET mutation prevalence in sporadic MTC is 44%." (PMID 40791984, 2025). "Germline-activating RET variants cause multiple endocrine neoplasia type 2 (MEN2), which is a hereditary cancer syndrome associated with medullary thyroid cancer (MTC) in nearly 100% of patients and pheochromocytoma (PCC) in approximately 50% of patients." (PMID 40725174, 2025). "It is noteworthy that all medullary thyroid cancer samples (i.e., THT_1–50) expressed wild-type RET at a high level." (PMID 41373459, 2025). "The LIBRETTO-531 trial represents a landmark phase III study demonstrating the superiority of selective RET inhibition in medullary thyroid cancer." (PMID 41595456, 2025). "Cabozantinib, another multikinase inhibitor with activity against VEGFR, MET, and RET, is approved for medullary thyroid cancer and as a second-line option in differentiated thyroid cancer." (PMID 41228293, 2025). "This cohort study evaluates medullary thyroid cancer risk and mortality in individuals with incidentally identified multiple endocrine neoplasia type 2A (MEN2A) RET variants and these differ from clinically ascertained cases." (PMID 40577012, 2025). "In medullary thyroid cancer xenografts, the combined effect of miR-153-3p, which targets RET, and cabozantinib was tested." (PMID 40283927, 2025).
medullary thyroid carcinoma (continued). "Somatic RET testing also remains insufficiently incorporated in the routine management of medullary thyroid carcinoma, despite its value in guiding the use of selective RET inhibitors and improving therapeutic decision-making." (PMID 41465145, 2025). "Abnormal RET activation resulting from missense variants, gene fusions, or overexpression has been associated with various human diseases, including medullary thyroid carcinoma (MTC), Hirschsprung’s disease, and pheochromocytoma." (PMID 41465145, 2025). "Vandetanib similarly targets VEGFR, EGFR, and RET and is approved for advanced medullary thyroid cancer, providing durable disease control in this rare subtype." (PMID 41228293, 2025). "Recently, somatic cell-based BRAF gene testing was performed on the papillary carcinoma region, and somatic cell-based RET gene testing was conducted on the medullary carcinoma region." (PMID 41323380, 2025). "Gain-of-function gene alterations in rearranged during transfection (RET), a receptor tyrosine kinase, are observed in both sporadic and hereditary medullary thyroid cancers (MTCs) and pheochromocytomas and paragangliomas (PPGLs)." (PMID 40725174, 2025). "In sporadic medullary thyroid carcinomas (MTC), in which the majority harbor RET mutations, up to 20% can have mutually exclusive alterations in the RAS family of genes, with the most common being an HRAS p.Q61R mutation." (PMID 40111709, 2025). "The most common neuroendocrine neoplasm of the thyroid gland is medullary thyroid carcinoma (MTC), which commonly possesses RET protooncogene mutations." (PMID 40426858, 2025). "Selpercatinib’s expedited approval in 2020 has provided another treatment option for patients with metastatic RET fusion-positive NSCLC and metastatic RET mutant medullary thyroid cancers." (PMID 41179283, 2025). "In the present study, we observed significant overexpression of wild-type RET in all medullary thyroid cancer samples (THT_1–50)." (PMID 41373459, 2025). "RET germline pathogenic variants cause multiple endocrine neoplasia type 2 (MEN2), which is associated with medullary thyroid cancer." (PMID 40577012, 2025). "Vandetanib, a multi-kinase inhibitor with RET kinase inhibitory activity, has been enlisted against medullary thyroid cancer." (PMID 39272672, 2024). "In this report, the authors present three cases of advanced mutant RET medullary thyroid cancer or lung adenocarcinoma, where the tumor responses to selpercatinib were measured using 2-deoxy-2-(18F)fluoro-D-glucose (18FDG)-PET/CT." (PMID 39272672, 2024). "Two case reports showed that one patient with RET fusion positive NSCLC and ten patients with RET-mutated medullary thyroid carcinoma treated with selpercatinib experienced intestinal edema." (PMID 39199650, 2024). "For example, in a patient receiving selpercatinib for RET-mutant medullary thyroid carcinoma, the addition of larotrectinib at the time of progression to address the emergence of NTRK fusion in a liquid biopsy analysis led to disease control." (PMID 39410015, 2024). "In contrast, another study involving 160 subjects with RET change (c.2410G > A), (p.Val804Met) indicated the penetrance of medullary thyroid carcinoma to be approximately 85% by the age of 70." (PMID 38802890, 2024). "Selpercatinib is a novel agent which received accelerated approval in 2020 for the treatment of RET-mutant malignancies including nonsmall cell lung cancer, medullary thyroid cancer, and other RET-fusion positive thyroid malignancies." (PMID 39148638, 2024). "Mutations in the RET proto-oncogene occur in about 25% of medullary thyroid carcinomas, leading to hereditary cancer syndromes such as MEN2A and MEN2B." (PMID 39598383, 2024). "These inhibitors have shown remarkable clinical efficacy, particularly in RET-driven lung cancer, medullary thyroid cancer, and other solid tumors driven by RET gene fusions." (PMID 39272672, 2024).